TNC (tenascin C)
Diseases named in the same sentence as TNC in open-access papers (continued):
Sharing a sentence is not in itself a finding about the gene and the disease.
tendinopathy (11 papers, 2013 to 2025). "The main purpose of this study was to investigate how the functional polymorphisms within the COL5A1, COL27A1 and TNC genes impact the risk of developing tendinopathies in high-level Croatian athletes." (PMID 40869983, 2025). "The glycoprotein tenascin-C is known to be present in healthy tendon and is involved in the regulation of collagen fibrillogenesis, but is also associated with tendon disease." (PMID 25412928, 2014). "Considering previous studies conducted on other populations, this study investigated further variations within COL5A1, COL27A1 and TNC genes and related risks of developing tendinopathies." (PMID 40869983, 2025). "In tendons, tenascin-C is highly expressed at sites of high mechanical strain, including myotendinous and osteotendinous junctions, and its upregulation is observed in pathological conditions such as tendinopathy." (PMID 40869983, 2025). "We investigated the potential influence of single nucleotide polymorphisms (SNPs) in fibrillin-2 (FBN2), tenascin-C (TNC), and matrix metalloproteinase-3 (MMP3) on the tendon regeneration failure phenotype and impact on the susceptibility to tendinopathy in Brazilian high-performance athletes." (PMID 39594135, 2024). "Also, upregulation of genes encoding proteoglycans (BGN) glycoproteins (TNC, FN1, SPARC), integrins (ITGB1), and growth factors has been reported in tendinopathy patients." (PMID 38001919, 2023). "Tenascin-C expression is sensible to mechanical strain and it is upregulated with tendinopathy." (PMID 32937830, 2020). "BGN and TNC were upregulated in tendinopathy, while DCN showed no change." (PMID 35008516, 2021).
glaucoma (10 papers, 2017 to 2023). Increased pressure in the eyeball due to obstruction of the outflow of aqueous humor. "In a rat model of glaucoma, tenascin-C mRNA was significantly increased in the ONH with early ON damage, and remained significantly elevated throughout the glaucoma progression compared to controls." (PMID 37686046, 2023). "The knock-out of tenascin-C was able to inhibit both microgliosis and astrogliosis in a mouse model of glaucoma, indicating its ability to act upon both of these cell types through TLR4 signaling." (PMID 37686046, 2023). "In a mouse glaucoma model, increased fibronectin, laminin, and tenascin-C levels were also found in the glaucomatous heterozygous retina and optic nerve compared to the wild-type group." (PMID 35269741, 2022). "As an endogenous activator of the TLR4, tenascin-C’s inflammatory role is being studied in glaucoma research." (PMID 35269741, 2022). "In agreement with the studies described, we show an IOP-dependent change of tenascin-C in the retina and optic nerve in our glaucoma mouse model." (PMID 33668263, 2021). "Upregulation of tenascin-C has been described in various eye diseases, such as diabetic retinopathy and glaucoma." (PMID 33668263, 2021). "In line with this and other studies, a dramatic upregulation of tenascin-C in murine retinal tissues of intraocular pressure-dependent glaucoma models has been described as part of an extensive remodeling of ECM molecules associated with glaucomatous neurodegeneration." (PMID 36936905, 2023). "Importantly, tenascin-C levels are prominent in the LC region of the ONH in elderly donor eyes, implicating increased levels with age, a potent risk factor for glaucoma development." (PMID 37686046, 2023). "Along with TLR4 expression differentiation, DAMPs such as tenascin-C and FN+EDA have also been identified as differentially expressed in the ONH and retina in glaucoma." (PMID 37686046, 2023). "Functionally, tenascin-C is known to regulate TGFβ signaling during wound healing, an important pathway involved in the changes to the ONH and LC in glaucoma." (PMID 37686046, 2023). "In patients with glaucoma and glaucoma animal models, astrocytes at the ONH can be observed to upregulate the expression of tenascin-C, playing a pro-inflammatory role through the Toll-like receptor (TLR) 4 signaling pathway." (PMID 34121982, 2021). "Consistent with mass spectrometry findings, we observed that A2M, B2M, Clusterin, TNC, FVII, Adiponectin, CRP, SAA, ICAM-1 and VCAM-1 were differentially affected in the retinas and vitreous of glaucoma subjects." (PMID 28978942, 2017). "Finally, the matricellular proteins periostin (PN) and TNC were studied, in a target analysis, in the aqueous humor of NVG patients, obtaining significantly higher levels when comparing glaucoma patients with subjects diagnosed with proliferative diabetic retinopathy." (PMID 34439995, 2021). "It is therefore tempting to speculate that tenascin-C-mediated signaling plays an important role in the activation and migration of astrocytes and microglia, which has a harmful effect on RGC survival in our glaucoma mouse model." (PMID 33668263, 2021).
liver fibrosis (10 papers, 2010 to 2025). "In this study, we aimed to evaluate whether CAR-Ms targeting TNC (TNC-CAR-Ms) can alleviate liver fibrosis and explore the underlying antifibrotic mechanism of TNC-CAR-Ms in vivo." (PMID 41214839, 2025). "In addition, this carotenoid correlated inversely with liver function markers alanine aminotransferase (ALT) and γ-glutamyl transpeptidase (GGT) and liver fibrosis associated marker Tenascin C (TENC4 and TNC)." (PMID 28194237, 2017). "The role of TNC in liver fibrosis was studied in established Tnc knockout (KO) and littermate control mice." (PMID 41214839, 2025). "Hepatic stellate cell (HSC) activation is present in the progression of liver fibrosis, secreting extracellular matrix proteins as tenascin-C (TnC)." (PMID 32392811, 2020). "We first investigated TNC expression in clinical patients with different liver fibrosis stages." (PMID 41214839, 2025). "In the bleomycin model, cannabidiol prevented skin fibrosis and collagen accumulation around skin blood vessels, and in the CCl4 model cannabidiol significantly attenuated liver fibrosis measured by picrosirius red and Tenascin C staining and reduced T cell and macrophage infiltration." (PMID 36339540, 2022). "In the liver, tenascin-C knockout mice with liver fibrosis induced by concanavalin A showed protection against collagen deposition and inflammatory cell infiltration, reduced IFN-γ, TNF, IL-4, and TGF-β1 production, and a lower number of activated HSCs in respect to wild type animals." (PMID 33262757, 2020). "This may be directly related to MTA antifibrotic effects, since tenascin-C is required for the development of experimental liver fibrosis." (PMID 21209952, 2010). "Ultimately, tenascin-C triggers inflammatory and fibrotic reactions and induces the progression of liver fibrosis by increasing the aggregation of hepatic stellate cells and the release of cytokines and TGF-β during the progression of hepatic fibrosis." (PMID 39114190, 2024).
autoimmune disease (9 papers, 2017 to 2025). A disorder resulting from loss of function or tissue destruction of an organ or multiple organs, arising from humoral or cellular immune responses of the individual to their own tissue constituents. "Increased expression of ECM components such as fibronectin and tenascin C in cancer and autoimmune diseases is well-documented." (PMID 35906512, 2023). "Increased expression of tenascin-C, OPN and TSP-1 is associated with autoimmune diseases, while collagen immunosuppressive receptor LAIR-1 decreases in chronic autoimmune disease." (PMID 33262757, 2020). "In contrast, the sustained high expression of tenascin-C is common in inflammation, tissue remodeling, and autoimmune diseases." (PMID 30442110, 2018). "Accumulating studies have revealed that matricellular proteins, including osteopontin and tenascin-C, both of which interact with integrin heterodimers, are involved in inflammatory diseases, autoimmune disorders, and cancers." (PMID 29065446, 2017). "Tenascin-C plays an immunomodulatory role in neuroinflammatory as well as autoimmune diseases." (PMID 33668263, 2021). "Recently, TNC, OPN and common receptor integrin-α9β1 have been identified as promising treatment targets for more autoimmune inflammatory diseases, since both TNC- and OPN-deficient mice have shown resistance against a variety of Th1- and/or Th17-related autoimmune diseases." (PMID 33790909, 2021). "High expression of tenascin-C is found in inflammation, tissue remodeling, and autoimmune diseases." (PMID 30442110, 2018). "Previous studies in the relevant literature investigated autoimmune diseases and tenascin-C levels, yet this is the first study on the relationship between FMF and tenascin-C." (PMID 39114190, 2024). "While in vivo targeting of fibronectin extra-domain A is well-characterized for molecular imaging and drug delivery in various autoimmune diseases including IBD, the previously identified D domain of tenascin C is largely unexplored for gastrointestinal diseases." (PMID 35906512, 2023).
COVID-19 (9 papers, 2021 to 2023). A disease caused by infection with severe acute respiratory syndrome coronavirus 2. "Exosomal analysis from COVID-19 patients revealed high levels of tenascin-C (TNC) and fibrinogen-β (FGB) compared to controls." (PMID 36077138, 2022). "We recently found that tenascin-C and fibrinogen-β are highly abundant in exosomes from COVID-19 patient plasma samples." (PMID 35587188, 2022). "Subsequently, we showed that exosomes from COVID-19 patients trigger inflammatory signals to hepatocytes by inducing NF-κB through tenascin-C and fibrinogen-β." (PMID 35587188, 2022). "In this study, we observed that exosomes from the plasma of COVID-19 patients harbor tenascin-C and fibrinogen-β, and trigger inflammatory signal in distant cells." (PMID 33804769, 2021). "Exosomes from plasma of severe cases (ICU) of COVID-19 had an increased level of the fibrosis markers tenascin-C (TNC) and fibrinogen-β (FGB)." (PMID 34638812, 2021). "We showed previously that tenascin-C and fibrinogen-β are highly abundant in exosomes from COVID-19 patients, which activate NF-κB in hepatocytes, and may play a role in this process." (PMID 35587188, 2022). "A recent study showed that EVs isolated from the plasma of COVID-19 ICU patients contained an elevated amount of D-dimer values, tenascin-C (TNC) and fibrinogen-β (FGB) relative to that of healthy controls i.e., volunteers who had not contracted the disease." (PMID 37829171, 2023). "Our results revealed that tenascin-C (TNC) and fibrinogen-β (FGB) are highly abundant in exosomes from COVID-19 patients’ plasma compared with that of healthy normal controls." (PMID 33804769, 2021). "Enhanced TNC and FGB expression in exosomes isolated from COVID-19 patients was verified by Western blot analysis." (PMID 33804769, 2021). "Tenascin-C (TNC) and fibrinogen-β (FGB) were identified as the two significantly enriched molecules in exosomes from COVID-19 patients relative to normal exosomes." (PMID 33804769, 2021). "Although another proinflammatory member of this family (i.e., Tenascin C) has been identified in the exosomes of COVID-19 patients, no data on Tenascin R could be found in COVID-19-related literature." (PMID 36012423, 2022). "Indeed, tenascin-C (TNC) and fibrinogen-β (FGB), which stimulate proinflammatory cytokines through the nuclear factor-κB (NF-κB) pathway, are widely abundant in plasma exosomes of COVID-19 patients compared to healthy subjects." (PMID 34440265, 2021).
dilated cardiomyopathy (9 papers, 2013 to 2025). Cardiomyopathy which is characterized by dilation and contractile dysfunction of the left and right ventricles. "The mutations in TnC, TnI and myosin heavy chain have been studied in vitro and the familial dilated cardiomyopathy phenotype is well established." (PMID 29093449, 2017). "The concentrations of circulating tenascin-C (TN-C) are elevated in autosomic dominant-EDMD and X-linked-EDMD patients and in some X-linked-EDMD carriers, allowing an identification of EDMD patients at risk of dilated cardiomyopathy." (PMID 33801069, 2021). "Additionally, key components of hypertrophic and dilated cardiomyopathy pathways (Rno05410; Rno05414), including ITGA, NCX, and TnC, were downregulated." (PMID 40598158, 2025).
gastric cancer (9 papers, 2007 to 2025). A primary or metastatic malignant neoplasm involving the stomach. "For instance, TNC is highly expressed in breast, esophageal, liver, colorectal, and gastric cancers and is associated with malignant progression and poor prognosis." (PMID 39915455, 2025). "Recent studies have shown that the expression of TNC was significantly associated with pT stage, lymph node metastasis and distant metastasis in gastric cancer." (PMID 34588421, 2021). "The results showed that VM exists in gastric cancer, consistent with previous studies, and TNC expression had a positive correlation with VM in gastric cancer tissues." (PMID 34588421, 2021). "The migration of AGS, BGC-823 and Hs746T cells was evaluated through wound-healing and transwell migration assays, indicating that TNC knockdown inhibited the migration rates of gastric cancer cells." (PMID 34588421, 2021). "Since VM formation is closely related to the proliferation, invasion and migration of tumor cells, we evaluated the detailed role of TNC in gastric cancer cells." (PMID 34588421, 2021). "Recent studies demonstrated that TNC was strongly expressed and indicated poor prognosis in gastric cancer." (PMID 34588421, 2021). "Then, we evaluated VM formation in gastric cancer cell lines and found that TNC knockdown inhibited the VM formation ability in vitro and in vivo." (PMID 34588421, 2021). "Then we evaluated the expression of TNC in 66 postoperative specimens of gastric cancer patients and found that TNC expression was significantly correlated with tumor size, AJCC stage, T stage and N stage." (PMID 34588421, 2021). "We examined the expression of TNC by western blot in five gastric cancer cell lines, including MKN-45, AGS, Hs746T, BGC-823 and MGC-803 and found that TNC was highly expressed in AGS, BGC-823 and Hs746T cell lines." (PMID 34588421, 2021). "Concurrently, knockdown of TNC also inhibited the migration and invasion of gastric cancer cell in vitro and inhibited peritoneal metastasis in vivo." (PMID 34588421, 2021). "Subsequently, we examined the mRNA and protein levels of phospho-ERK, MMP2/9 and markers of EMT and found that phpspho-ERK, MMP2/9 were significantly decreased and gastric cancer cells was induced to proceed mesenchymal-to-epithelial transition process upon TNC knockdown." (PMID 34588421, 2021). "Furthermore, knockdown of TNC significantly inhibited VM formation and proliferation of gastric cancer cells in vitro and in vivo, with a reduction in cell migration and invasion." (PMID 34588421, 2021). "Thus, we used Gene Set Enrichment Analysis to analyze the correlation between TNC expression in gastric cancer and activation of the MAPK pathway and found a significant positive association between TNC expression and activation of the ERK pathway." (PMID 34588421, 2021). "In the present study, we investigate the role of tenascin-c (TNC) in the formation of VM in gastric cancer and found that TNC was upregulated in gastric cancer tissue than in the corresponding adjacent tissues and correlated with VM and poor prognosis of gastric cancer." (PMID 34588421, 2021). "The present results confirmed that TNC was upregulated in gastric cancer tissues and had a positive correlation with VN, and patients with higher TNC levels had significantly shorter OS and RFS compared to those with low TNC expression, consistent with our single-center data." (PMID 34588421, 2021). "Our data show that the signaling pathways stimulated by PAR1 in the gastric cancer-derived cells mediate proliferation and invasion, and Tenascin-C (TN-C) might play an important role in this signaling pathways stimulated by PAR1." (PMID 20723226, 2010). "Our findings suggest that TNC may represent a novel target in the treatment of gastric cancer." (PMID 34588421, 2021). "Our previous study reported that CDH11-mediated juxtacrine interaction of gastric cancer cells and fibroblasts promotes metastasis via YAP/tenascin-C." (PMID 38462626, 2024).
gastric cancer (continued). "Flow cytometry also showed that TNC knockdown increased Annexin V-positive cells in AGS, BGC-823 and Hs746T cells indicating that TNC knockdown induced apoptosis in gastric cancer cells." (PMID 34588421, 2021). "However, the role of TNC in VM formation and EMT in gastric cancer was not reported." (PMID 34588421, 2021).
keloid (9 papers, 2008 to 2026). An irregularly shaped, elevated mark on the skin caused by deposits of excessive amounts of collagen during wound healing. "Increased expression of tenascin C was observed during keloid formation in association with collagen fibrils in the reticular dermis, whereas tenascin C was only expressed beneath the basal lamina in normal skin." (PMID 37587491, 2023). "Immunohistochemical changes in TNC expression have also been used in previous literature to evaluate the efficacy of different keloid treatments." (PMID 35444665, 2022). "The protein expression level expression of TNC has been verified in previous studies to be significantly different in normal skin and keloid tissue." (PMID 35444665, 2022). "In recent years, TNC has been widely studied for its important role in wound healing and the pathogenesis of keloid." (PMID 35837392, 2022). "Then we used our RNA sequencing data to verify the expression of TNC in keloid and normal tissue and found that TNC was also up-regulated in keloids." (PMID 35003102, 2021). "We next conducted qRT-PCR experiment on 16 keloid patients, from whom the keloid tissue and peri-keloid normal tissue were taken for TNC mRNA quantification." (PMID 35003102, 2021). "In the group with high TNC expression, the content of M0 in macrophages was lower, which provided a reference for further exploration of the immune microenvironment of keloid." (PMID 35003102, 2021). "It is suggested that the TNC gene has a good effect on the diagnosis of keloid fibrous tissue and normal fibrous tissue." (PMID 35003102, 2021). "However, in keloids, TNC expression is diffusely distributed in fibroblasts and collagen fibers in the dermis." (PMID 35444665, 2022). "The authors identified a novel keloid biomarker, Tenascin-c(TNC), by single-cell analysis, weighted co-expression network analysis, and differential gene analysis, and verified TNC expression by RNA-sequencing in clinical keloid samples." (PMID 35444665, 2022). "We identified the sensitive biomarker of keloid: Tenascin-C (TNC)." (PMID 35003102, 2021). "These evidences all suggest that TNC may be a potential target for keloid therapy in the future." (PMID 35837392, 2022). "Subsequent network topology analysis through CytoHubba identified six hub genes (IL6, POSTN, VCAN, COL11A1, HAPLN1, TNC) via three methods of calculation respectively (Closeness, Degree and EPC), representing key regulatory nodes in the keloid." (PMID 41544047, 2026). "As a result, there were 25 known keloid-related genes reported among the analyzed genes, whereas two pairs of them (COL14A1 and TNC, COL1A2 and PEPD) were co-occurred in the literature that mentioned the curated keyword 'keloid' (data not shown)." (PMID 18620599, 2008). "The expression of TNC in the epidermis of normal skin and keloid tissue was negative." (PMID 35444665, 2022). "However, the mechanism of TNC’s role in the pathological process of keloids has not been fully elucidated." (PMID 35444665, 2022).